SOST (sclerostin)
Diseases named in the same sentence as SOST in open-access papers (continued):
Sharing a sentence is not in itself a finding about the gene and the disease.
cancer (36 papers, 2013 to 2025). A tumor composed of atypical neoplastic, often pleomorphic cells that invade other tissues. "Background/Objectives: This study aims to investigate the association of movement behaviors with irisin, sclerostin, and bone turnover markers in young pediatric cancer survivors." (PMID 39599700, 2024). "Therefore, the aim of the study was to investigate the associations of PA with irisin, sclerostin, and bone turnover markers in young survivors of pediatric cancer." (PMID 39599700, 2024). "Among the identified FRGs, MYBPH, SOST, SPRR2A, and CRNN were notably upregulated in the high-risk group, implying their potential involvement as cancer-promoting genes in BLCA development." (PMID 38172792, 2024). "Sclerostin is a vital inhibitor Wnt/ β-catenin signaling pathway which plays a role in cardiovascular diseases and cancer." (PMID 37759285, 2023). "As discussed in more detail in Section 5 and Section 6, targeting osteocyte-derived factors regulating bone resorption (i.e., RANKL) or formation (i.e., sclerostin or DKK-1) also has an impact on the progression of cancers that grow in bone." (PMID 37174109, 2023). "Sclerostin is a classical inhibitor of Wnt/β-catenin signaling, which is involved with many diseases, such as cancer, eye disease, and bone diseases." (PMID 37759285, 2023). "The Wnt antagonist SOST was also reported to enhance cancer-induced osteolytic bone metastasis, and its inhibition prevented osteolytic lesion formation in MDA-MB-231 and MCF7 xenograft models." (PMID 36497192, 2022). "In order to counteract the cancer-induced osteolysis, bone-anabolic agents (e.g., Romosozumab, an antibody against Sclerostin), which are used in clinical practice to treat osteoporosis, are currently emerging as promising treatment approaches." (PMID 35158995, 2022). "The secretion of sclerostin by cancer cells is a notable finding as in its physiological context sclerostin is secreted by osteocytes to antagonize WNT signaling, resulting in suppression of bone formation." (PMID 34503118, 2021). "Evaluating the contribution of osteocyte-specific markers – FGF23, sclerostin, Dkk-1 – is important, as these proteins have gained attention as potential targets in cancer treatments." (PMID 30568232, 2018). "The role of sclerostin in cancer and SOSTDC1 (sclerostin domain containing 1)-expression in cancerous tissue was addressed in several studies." (PMID 27666393, 2016). "This could be explained by the lower levels of sclerostin in our sample of young pediatric cancer survivors (mean 101.4 vs. 117.9 pg/mL), which might influence the catabolic activity on the bone." (PMID 39599700, 2024). "Moreover, DSG1, C6orf15, SOST, SPRR2A, SERPINB7, MYBPH, and KRT1 were considerably expressed in the high-risk group, indicating their potential roles as cancer-promoting genes in the development of BLCA." (PMID 37664033, 2023). "Additionally, we observed significant expression of CLDN6, CES1, SOST, SPRR2A, MYBPH, CGB5, and KRT1 in the high-risk group, suggesting their potential involvement as cancer-promoting genes in BLCA development." (PMID 37780567, 2023). "Accumulated evidence has demonstrated that SOST mediates cancer progression." (PMID 35785219, 2022). "Indeed, sclerostin-antibody treatment altered the number and activity of osteoblasts and osteoclasts in vivo, protected against cancer-induced bone destruction, and reduced the bone-metastatic burden in mouse models of breast cancer bone metastasis." (PMID 35158995, 2022). "In addition, the Wnt inhibitors DKK1 and SOST secreted by MSCs, osteocytes or cancer cells were found to induce slow cycling or a dormant state in multiple myeloma, breast, lung and liver cancers." (PMID 36497192, 2022). "In other words, because sclerostin is an inhibitor of bone formation, its administration could exacerbate osteolytic metastases that occur in other cancers." (PMID 34885123, 2021).
cancer (continued). "Furthermore, cancer metastasis-induced inflammation upregulates osteocytic sclerostin that inhibits osteoblast function." (PMID 32733380, 2020). "Sclerostin is emerging as a potential target to treat cancer-related bone diseases." (PMID 32188434, 2020). "They found that SOST (Sclerostin) was widely expressed in osteocytes within the 3D tissue cultures, but SOST expression was significantly decreased when osteocytes were cocultured with CR cancer cells." (PMID 32478897, 2020). "Anti-sclerostin drugs have been tested in patients with low bone mass, and the results of phase I and II trials opened the way to the clinical investigation of these agents in cancer-induced bone disease." (PMID 32640686, 2020). "Another important mediator of cancer induced bone pain is osteocyte-derived Sclerostin (SOST)." (PMID 30641973, 2019). "Furthermore, we have yet to determine if DKK1 and SOST are similarly processed by cancer cells." (PMID 26545120, 2015). "High expression of Wnt antagonists (i.e., sclerostin and DKK-1) has been detected in cancer patients with bone involvement and mouse models of cancer in bone, suggesting osteocyte production of these factors is affected by cancer cells in bone." (PMID 37174109, 2023). "In addition, similar with sclerostin, Dickkopf-1 (Dkk1), another inhibitor of the canonical Wnt signaling pathway, has also been proven to participate in the canonical Wnt signaling pathway, and to promote the β-catenin independent Wnt signaling in many types of cancers." (PMID 33717084, 2021). "Sclerostin, DKK-1, and FGF23 are osteocyte-specific markers; they were studied to evaluate their contribution to osteocyte/cancer cell crosstalk." (PMID 32640686, 2020). "While sclerostin is almost exclusively expressed in osteocytes, DKK1 is secreted by a variety of different cells and tissues including cancer cells." (PMID 30227689, 2018). "But so far, the research about the roles of sclerostin in the non-canonical Wnt pathway in cancers are still lacking, which deserves more attention and effort of further exploration." (PMID 33717084, 2021). "Since SOST’s role in cancer has been minimally explored, it also remains to be elucidated whether this molecule, similar to DKK1 has context-dependent effects on cancer." (PMID 26545120, 2015). "Interestingly, the effect of SOST on cancer invasion/metastasis has never been investigated." (PMID 26545120, 2015). "To date, the effects of dual inhibition of sclerostin and DKK-1 in cancer models have not been investigated." (PMID 37174109, 2023).
cardiovascular disease (32 papers, 2013 to 2025). "In analyses of serum/tissue sclerostin levels in patients with cardiovascular diseases, the results were controversial but indicated an association between sclerostin and the presence/severity/outcomes of cardiovascular diseases." (PMID 40429697, 2025). "If a SOST inhibitor targets the loop 2 of SOST it will be associated with increased risk for the development of cardiovascular diseases, similar to romosozumab." (PMID 36581888, 2022). "Human studies have associated high circulating sclerostin levels with the presence of different cardiovascular diseases (CVD), surrogate CVD markers, and a high risk of cardiovascular events in some populations." (PMID 36498053, 2022). "Taken together, an association between low sclerostin expression and cardiovascular disease appears epidemiologically possible, but seems unlikely based on the current understanding of the functions of sclerostin and experimental data." (PMID 34822428, 2021). "Regarding the other identified proteins, recent studies have shown that SOST plays essential roles in bone formation, modelling and remodelling and is linked to bone physiology and cardiovascular disease." (PMID 32701210, 2020). "However, this breakthrough in improving bone mass through sclerostin inhibition has raised significant concerns about the potential increase in the risk of cardiovascular diseases, including myocardial infarction and stroke." (PMID 40307216, 2025). "The association between serum sclerostin and the presence of cardiovascular diseases." (PMID 40429697, 2025). "Additionally, monitoring calcium and phosphorus metabolism, along with inflammatory markers (e.g., hs-CRP, SOST), can further reduce the risk of cardiovascular disease." (PMID 40314886, 2025). "Overall, the evidence suggests that sclerostin inhibition may increase the risk of cardiovascular disease, and further assessment of cardiovascular risk is needed when considering treatment with romosozumab." (PMID 38093031, 2024). "The role of sclerostin in cardiovascular disease has been studied in other settings outside of CKD; see Golledge and Thanigaimani for an exhaustive review." (PMID 36776982, 2023). "One explanation is that the high blood sclerostin concentrations in participants with cardiovascular disease represent a response to the disease serving as a brake rather than a cause." (PMID 36776982, 2023). "Sclerostin is an independent risk factor for aortic calcification, and the determination of serum sclerostin in hemodialysis patients is helpful to prevent cardiovascular disease." (PMID 34976409, 2021). "A number of studies investigated the association between serum sclerostin and pulse-wave velocity (PWV, a measure of vascular stiffness and surrogate parameter for cardiovascular disease), as well as patient mortality." (PMID 34822428, 2021). "Sclerostin could participate in protecting the cardiovascular system for individuals with a history of cardiovascular disease." (PMID 40429697, 2025). "The investigation of tissue levels of sclerostin in cardiovascular diseases may facilitate understanding of the role of sclerotin in the cardiovascular system." (PMID 40429697, 2025). "Sclerostin is an important inhibitor of the Wnt/β-linker protein signaling pathway, which is not only closely related to bone metabolism, but also plays a role in a number of other target molecules, including cardiovascular disease and cancer." (PMID 39808360, 2025). "Recently, two larger epidemiological studies on the association between sclerostin gene polymorphisms, which are associated with a low sclerostin expression phenotype (thus mimicking therapeutic intervention in sclerostin levels) and cardiovascular disease have been published." (PMID 34822428, 2021). "However, few studies have shown that the interaction between sclerostin and miRNA-29b affects vascular calcification and cardiovascular disease in patients receiving hemodialysis." (PMID 34976409, 2021).
cardiovascular disease (continued). "However, the mouse strain used for the sclerostin gene-knock-out studies (C57/Bl6) is widely known to be resistant to cardiovascular disease, which is a limitation of the murine studies in terms of cardiovascular pathology." (PMID 34822428, 2021). "However, few studies have investigated the influence of sclerostin on cardiovascular disease prognosis." (PMID 31677125, 2020). "In CKD stage 5D patients, male gender, hemodialysis as modality, history of cardiovascular disease (CVD), higher age and phosphate and lower bicarbonate, PTH (both assays), residual renal function, and blood platelets all were significantly associated with higher serum sclerostin levels." (PMID 28493902, 2017). "Nonetheless, the potential association between SOST variations in the coding region and cardiovascular risk indicated that these variations might influence cardiovascular diseases through changes in protein conformation rather than solely affecting gene expression levels." (PMID 40429697, 2025). "Specifically, large-scale prospective studies are needed to evaluate the impact of sclerostin on CKD–MBD and whether sclerostin can be used to monitor treatment response in BMD and cardiovascular disease in KTRs." (PMID 39078512, 2024). "Experimental studies have not shown adverse effects of sclerostin inhibition on cardiovascular disease outcomes." (PMID 38093031, 2024). "Previous studies reported that serum sclerostin gradually increases from non-uremic controls without overt calcification-related cardiovascular disease to those with AVC, and from uremic patients without AVC to their counterparts with AVC." (PMID 30314461, 2018). "Both sclerostin and DKK1 may be considered mediators and markers of cardiovascular disease (CVD)." (PMID 28493902, 2017).
kidney disease (12 papers, 2013 to 2025). "The upregulation of sclerostin in calcified tissues led researchers and clinicians to come up with a hypothesis that sclerostin may be related to the pathogenic mechanism of vascular calcification in renal disease patients." (PMID 36498053, 2022). "Human studies have been using the sclerostin as an angiogenic marker for patients with kidney disease and this is also a marker that can be better explored in further experimental studies in our Vit.D deficiency model." (PMID 31426337, 2019). "Sclerostin levels increases with the progression of kidney disease, and is potent inhibitor of bone formation, and therefore suggested to reduce vascular calcification." (PMID 29571288, 2018). "Laboratory measurements including fibroblast growth factor-23 and sclerostin, and quality of life assessed with the Kidney Disease Quality of Life-Short Form are also studied." (PMID 28460640, 2017). "Although the cardiovascular risk association with sclerostin has not been verified yet in CKD patients, sclerostin levels were found to be higher in CKD patients, which indicates the role of sclerotin in kidney disease." (PMID 40559238, 2025). "Sclerostin levels increase during progression of kidney disease and in patients on dialysis; however, it is not known whether this is the result of increased sclerostin production or decreased excretion." (PMID 28460640, 2017). "Fifty-four adults without relevant renal disease served as controls for serum sclerostin levels." (PMID 24112318, 2013).
metabolic disease (8 papers, 2019 to 2022). A congenital disorder (due to inherited enzyme abnormality) or acquired (due to failure of a metabolically important organ) disorder resulting from an abnormal metabolic process. "Therefore, serum sclerostin levels and metabolic disorders may both reflect underlying differences in kidney function rather than pathogenic overproduction of sclerostin." (PMID 33776907, 2021). "As described in the introduction section, the study findings on the sclerostin levels in these metabolic diseases were contradictory." (PMID 36124027, 2022). "Clinical studies demonstrate that serum sclerostin levels are positively correlated with fat mass and incidence of metabolic disorders." (PMID 33776907, 2021). "Sost-/- mice and mice treated with anti-sclerostin antibodies were resistant to metabolic disorders induced by an obesogenic diet." (PMID 33406758, 2021). "Specifically, serum sclerostin was closely associated with peripheral insulin sensitivity (HOMA2-%S), thus supporting the role of skeletal muscle/bone interactions in metabolic diseases." (PMID 33671861, 2021). "Nevertheless, correlations between circulating sclerostin and fat mass or metabolic disorders have inspired investigations into possible endocrine effects of sclerostin on adipose tissue." (PMID 33776907, 2021). "They suggest that sclerostin may be a promising therapeutic target for metabolic diseases and that sclerostin inhibitors (monoclonal antibodies, aptamers, and small-molecule inhibitors) could probably be used for patients in the future." (PMID 36124027, 2022). "Our results show that, even after the exclusion of underweight patients from the sample, SIRT1 maintained a positive role in regulating TBS, the bone structure most exposed to the effects of metabolic disorder, and sclerostin has a negative impact on BMD." (PMID 35267956, 2022).
vascular disorder (4 papers, 2018 to 2025). A general term used to describe any disease affecting blood vessels]. "Regardless of its function at the vascular level, the evidence indicates an association between increased levels of sclerostin with vascular disorders." (PMID 29928063, 2018). "While it is well established that sclerostin has extraskeletal functions, particularly in various vascular disorders, the precise mechanism by which it influences the VC process remains controversial." (PMID 38667470, 2024). "Sclerostin is a Wnt-signaling inhibitor, having a pathophysiological role in vasculopathy, and could be used as a vasculopathy marker." (PMID 40353858, 2025). "However, there is increasing evidence on the extraskeletal functions of sclerostin, pointing to its role in various vascular disorders." (PMID 29928063, 2018).
heart disease (3 papers, 2022 to 2024). "In confounder‐adjusted analyses, sclerostin was associated with an increased risk of death from cardiac disease during follow‐up (1.13; 1.03, 1.23)." (PMID 34738659, 2022). "Sclerostin might have a role as a molecular signal for PH, differentiate and better identify PH-left heart disease in ESKD patients." (PMID 38341544, 2024). "Furthermore, understanding the potential interplay between IGFBP3, ISLR, SOST, and paracrine/autocrine response is a pivotal step in the identification of new or improved drug targets for the treatment of heart disease." (PMID 39430425, 2024).
neurodegenerative disease (3 papers, 2016 to 2024). A disorder of the central nervous system characterized by gradual and progressive loss of neural tissue and neurologic function. "Additionally, disruption of the BBB has been reported in neurodegenerative diseases, such as PD, indicating that sclerostin can cross the BBB and reach the central nervous system." (PMID 39104397, 2024). "Consequently, inhibition canonical Wnt signalling via Wnt inhibitors such as SOST could be beneficial to promote FCSCs to repair fibrocartilage and potentially prevent degenerative disease." (PMID 27721375, 2016). "The serum level of several bone-derived mediators has been found modulated in patient affected by bone diseases, as osteoporosis, but also in the case of neurodegenerative diseases, such as AD [e.g., OCN, OPN, sclerostin, Dkk-1, and lipocalin 2] and PD [e.g., bone morphogenic protein 2, OCN]." (PMID 33995117, 2021). "The hypothesis is that sclerostin could be involved in the regulation of this pathway in neurodegenerative diseases, however, it has not been yet demonstrated whether sclerostin is able to cross the BBB, or not." (PMID 33995117, 2021).
infection (2 papers, 2023 to 2026). The state of being infected such as from the introduction of a foreign agent such as serum, vaccine, antigenic substance or organism. "Cellular production of sclerostin can be stimulated by infection, trauma, compression-induced inflammation, and the ischemic-hypoxic state caused by induration." (PMID 40323540, 2026). "Indirect evidence indeed suggests an active role of SOST in the host immune response to infection." (PMID 36943596, 2023).
Musculoskeletal diseases (2 papers, 2019 to 2024). "Sclerostin has been implicated in the pathogenesis of several Wnt-related musculoskeletal disorders." (PMID 38247829, 2024). "Musculoskeletal diseases: A strategy that has been proposed to treat musculoskeletal diseases via the WNT pathway is to develop inhibitors for WNT antagonists that are relevant to bone development, mainly DKK1 and sclerostin." (PMID 31382613, 2019).
bacterial infection (1 paper, 2019). "The effect of a bacterial infection on sclerostin expression is still unknown." (PMID 30924022, 2019).
brain disorder (1 paper, 2025). A disease affecting the brain or part of the brain. "Regarding the association of SOST with brain diseases, it has been suggested that plasma levels of the bone-derived protein SOST are positively correlated with cerebral Aβ load in a cognitively unimpaired elderly population." (PMID 40563496, 2025).